ANKUB1 (ankyrin repeat and ubiquitin domain containing 1)
Synonyms: C3orf16
Tractability: No criterion of Open Targets' tractability assessment is met for any kind of drug.
Gene: Protein-coding gene on chromosome 3 (149,761,100 to 149,968,385, reverse strand). Ensembl gene ENSG00000206199.
Genetic constraint (gnomAD): Loss-of-function variants: 42 observed, 50.14 expected, observed/expected ratio (o/e) 0.84, 90% interval 0.65 to 1.08. The upper end of that interval is the gene's LOEUF score, 1.08, which puts it in group 4 of 6, group 1 being the genes least tolerant of losing a copy. Missense variants: 590 observed, 635.74 expected, observed/expected ratio (o/e) 0.93, 90% interval 0.87 to 0.99. Synonymous variants: 216 observed, 229.99 expected, observed/expected ratio (o/e) 0.94, 90% interval 0.84 to 1.05.
Homologues: Orthologues: chimpanzee ANKUB1 (99% identical), macaque ANKUB1 (98% identical), pig ANKUB1 (86% identical), rabbit ANKUB1 (85% identical), mouse Ankub1 (79% identical), rat Ankub1 (78% identical), tropical clawed frog ANKUB1 (49% identical). Paralogues in human: ZFAND4 (12% identical), RPS27A (9% identical), UBC (9% identical), UBA52 (7% identical), UBL4B (7% identical), UBL4A (6% identical), NEDD8 (6% identical), UBD (5% identical), ISG15 (5% identical), UBB (3% identical).
Diseases named in the same sentence as ANKUB1 in open-access papers:
ANKUB1 is named in the same sentence as 2 diseases in open-access papers, as found by Europe PMC text mining. Sharing a sentence is not in itself a finding about the gene and the disease. The quoted sentences say what the papers report.
Polysyndactyly (2 papers, 2020 to 2024). Polysyndactyly or PPD4 is a form of preaxial polydactyly of fingers (see this term), a limb malformation syndrome, characterized by the presence of a thumb showing the mildest degree of duplication, being broad, bifid or with radially deviated distal phalanx. "In 2020, a report was published suggesting that frameshift mutations of GLI3, ANKUB1, and TAS2R3 might alter protein functions and accelerate the progression of polysyndactyly (PSD), an autosomal dominant genetic limb malformation." (PMID 38871700, 2024).
ANKUB1 also shares sentences with these, for which no sentence is quoted: Ataxia (1 paper).